S100B (S100 calcium binding protein B)
Diseases named in the same sentence as S100B in open-access papers (continued):
Sharing a sentence is not in itself a finding about the gene and the disease.
COVID-19 (continued). "Finally, the peripheral BBB indicator S100B was found elevated in the blood of COVID-19 patients, and correlated with disease severity." (PMID 39779630, 2025). "Our results, which demonstrate an increase in astrocyte-derived EVs and S100B in peripheral blood after COVID-19, support this hypothesis." (PMID 39349618, 2024). "To better understand how COVID-19 affects the BBB, we analyzed two independent biomarkers of astrocytes, astrocyte-derived extracellular vesicles (EVs) and S100B, in plasma samples obtained during the acute infection (baseline), and 4, 8, and 12 months after hospitalization for COVID-19." (PMID 39349618, 2024). "Moreover, in both groups before COVID-19, S100B was rarely detected, and values in the upper range of the standard curve accounted for 7%." (PMID 39519343, 2024). "This may suggest that the elevated levels of S100B represents CNS injury to some extent during the acute phase of COVID-19, but it is unclear what implications this may have both clinically and in long-COVID patients." (PMID 36268187, 2022). "Elevated levels of circulating S100B has also been found in different groups of COVID-19 patients." (PMID 36268187, 2022). "In our study, we found that S100B levels were higher in all COVID-19 cases compared with controls." (PMID 34836309, 2021). "Increased levels of MAP2, NSE and S100B indicate neuronal and astrocytic injury after COVID-19." (PMID 34838058, 2021). "However, the source of increased serum S100B in COVID-19 patients has yet to be identified." (PMID 35892571, 2022). "In patients with COVID-19, moderate correlations between the SBT at three months and E-Selectin at day 1 (r=-0.437, p = 0.007), S100B at day 3 (r = 0.553, p = 0.011) and S100B at day 7 (r = 0.496, p = 0.012) were observed." (PMID 39352661, 2025). "The results of the study showed that the S100B concentration in serum from patients with T2DM, from whom blood was collected before COVID-19, was detectable (≥7.8 pg/mL) in 7 out of 59 patients with T2DM, representing 11.9% of the entire group." (PMID 39519343, 2024). "The aim of this study was to investigate if COVID-19 is related to increased BBB permeability by analyzing leakage of biomarkers such as astrocyte-derived extracellular vesicles (EVs) and S100B." (PMID 39349618, 2024). "Nevertheless, many reports pointed towards an increase in the circulating markers of astrocyte activation, namely S100B and GFAP, during the acute COVID-19 phase." (PMID 39451987, 2024). "NE, S100B, and NSE are proteins whose potential significance has been demonstrated in patients with COVID-19." (PMID 39519343, 2024). "Based on the presented chart, it can be inferred that for the threshold value of S100B ≥ 7.8 pg/mL, the percentage of individuals with T2DM is significantly higher in the post-COVID-19 group compared to the pre-COVID-19 group (p < 0.05)." (PMID 39519343, 2024). "In contrast, levels of antibodies against tau protein (IgG), S100B (IgG), NMDA receptor (IgA), enteric nerve (IgG), amyloid β peptide (IgG), and GAD-65 (IgG) were lower in the sera of COVID-19 patients." (PMID 36832180, 2023). "Hyperalbuminorrachia and elevated levels of the astroglial protein S100B, suggestive of BBB dysfunction, were found in a small but extensive longitudinal study of COVID-19 patients with neurological manifestations." (PMID 37445634, 2023). "Serum S100B is a biomarker for cognitive impairment in patients with ESKD and also an indicator of COVID-19 severity." (PMID 36017003, 2022). "Plasma samples from 57 subjects at < 48 h of COVID-19 hospitalization, and 20 matched controls were interrogated for the levels of six BIMs—including GFAP, S100B, Syndecan-1, UCHLI, MAP2 and NSE, two EIMs—including sICAM1 and sVCAM1." (PMID 34838058, 2021). "To investigate the effects of COVID-19 on BIMs, we examined systemic levels of six previously validated BIMs—MAP2, NSE, GFAP, S100B, Syndecan-1 and UCHL1." (PMID 34838058, 2021).
COVID-19 (continued). "Three BIMs: MAP2, NSE and S100B, two EIMs: sICAM1 and sVCAM1 and seven CCs: GRO IL10, sCD40L, IP10, IL1Ra, MCP1 and TNFα were significantly (p < 0.05) elevated in the COVID-19 cohort compared to controls." (PMID 34838058, 2021). "At < 48 h hospitalization for of COVID-19, the mean levels of MAP2 (68 ± 7.5 vs. 26 ± 3.9, pg/ml, p < 0.01), NSE (16.9 ± 3.2 vs. 4.9 ± 0.59, pg/ml, p < 0.01) and S100B (113 ± 16 vs. 43 ± 7, pg/ml, p < 0.01) were significantly higher compared to controls." (PMID 34838058, 2021). "S100B levels are also found significantly higher in 38% of ICU admitted COVID-19 patients without any clinical evidence of brain injury." (PMID 41164170, 2025). "Serum S100B is a marker of clinical severity in SARS-CoV-2 infection and is involved in COVID-19." (PMID 40048451, 2025). "The pooled SMD for S100B COVID-19 with and without pneumonia was 0.30 [95% CI: 0.02, 0.57], indicating that S100B levels were moderately higher in COVID-19 pneumonia patients compared to those without pneumonia." (PMID 41585373, 2025). "In this multicenter study involving a large cohort of COVID-19 patients, serum NfL and S100B biomarkers were not accurate in discriminating cases with neurological manifestations from those without." (PMID 39779630, 2025). "When comparing COVID-19 patients with and without pneumonia, S100B was also higher in the pneumonia group (SMD = 0.30, 95% CI 0.02–0.57, p = 0.04)." (PMID 41585373, 2025). "It is worth noting that discrepancies exist regarding S100B and GFAP expression in acute COVID-19." (PMID 39451987, 2024). "IL-8, D-dimer, S100B, IL-6, Angpt-2, MMP-8, TNF-R1, u-PAR, u-PA, osteopontin, IL-13, TNF-α, pentraxin-3, P-selectin, fractalkine, and SP-D levels were elevated in critically ill COVID-19 males compared to severe cases." (PMID 39507250, 2024). "Finally, correlation between S100A6, S100B, S100A8, S100A9, S100A12, and S100P and COVID-19 pathogenesis is discussed." (PMID 35892571, 2022). "Understanding whether lymphocyte apoptosis has a functional role in the increased levels of S100B in ESKD, COVID-19, or RAGE-mediated responses may provide insight into immunity and disease progression." (PMID 36017003, 2022). "Additionally, we found that BIMs (NSE, S100β, tau, MAP2) were higher in men compared to women with COVID-19." (PMID 34838058, 2021). "Furthermore, blood levels of IL1α, calprotectin (a heterodimer made of S100A8 and S100A9), S100A12, S100B and HGBM1 appear to correlate with COVID-19 severity." (PMID 34293006, 2021). "This meta-analysis provides robust evidence that inflammatory biomarkers, particularly IL-6, IL-10, IL-8, and S100B, are significantly elevated in patients with COVID-19 pneumonia and organ failure compared to non-pneumonia COVID-19 patients and healthy controls." (PMID 41585373, 2025). "Besides, our results are in agreement with findings of no utility of S100B in determining COVID-19 acute severity, meant as necessity of respiratory support according to NIH classification." (PMID 39779630, 2025). "The aim of the study was to determine whether there is any justification for measuring NE, S100B, and NSE in patients with T2DM and NfT2DM who have recovered from COVID-19, suggesting that these proteins might play a role in building a predictive model for PCS." (PMID 39519343, 2024). "Additionally, Angpt-2, complement factor D, PAI-1, pentraxtin-3, S100B, tissue factor, TNF-R1, and u-PAR levels were associated with age in patients with severe, but not critical COVID-19." (PMID 39507250, 2024). "Levels of IgG antibodies against S100-B were significantly lower in COVID-19 patients regardless of disease severity when compared with the healthy control group, which could be explained by tissue consumption of autoantibodies." (PMID 36832180, 2023).
COVID-19 (continued). "Furthermore, among individuals admitted to an intensive care unit (ICU) for COVID-19, serum S100B levels were elevated in non-survivors compared to survivors, showing a notable correlation with inflammatory markers, such as lymphocyte counts and interleukin-6 (IL-6) levels." (PMID 39451987, 2024). "We identified higher levels of D-dimer, IL-6, IL-8, IL-13, Angpt-2, Pentraxin-3, S100B, MMP-8, and u-PAR in the plasma of critical COVID-19 non-survivors than in that of survivors." (PMID 39507250, 2024).
cerebral infarction (24 papers, 2011 to 2025). An ischemic condition of the brain, producing a persistent focal neurological deficit in the area of distribution of the cerebral arteries. "There was a high association between elevated serum S100B level and cerebral infarction as demonstrated on CT." (PMID 27007976, 2016). "Higher serum S100B level was found to be associated with cerebral infarction as diagnosed by CT (padj = 3.1 x 10−4) and worse GOS outcome (padj = 5.5 x 10−11)." (PMID 27007976, 2016). "Using a pooled analysis, we found higher serum S100B level to be associated with cerebral infarction and worse long-term outcome." (PMID 27007976, 2016). "According to our second observation, lower level of ficolin-3 in the follow-up samples were associated with greater size of the cerebral infarct indicated by higher S100β levels in the sera." (PMID 22206485, 2011). "In addition to cerebral infarction, there is a high association between elevated serum S100B level and worse long-term GOS outcome." (PMID 27007976, 2016). "The expression of ligands, such as HMGB1 and S100B, was much higher in the presence of cerebral infarction." (PMID 35725479, 2022). "We studied the expression of inflammation factors of RAGE, HMGB1, AGE, and S100B after cerebral infarction in rats treated with vx-765 to better understand the mechanism of RAGE in BBB damage." (PMID 33584203, 2020). "In one patient, who was confirmed for vasospasm and developed cerebral infarction, S100B levels showed a consequent peak." (PMID 30011792, 2018). "Several studies have described a significant increase in plasma levels of S100β protein within the first 3 days after cerebral infarction." (PMID 25029344, 2014). "A correlation has been observed between plasma levels of S100β protein and the size of cerebral infarction." (PMID 25029344, 2014). "In recent years, studies have shown that S100B is useful as a predictive marker for outcome after cerebral infarction, anoxic brain injury, and SAH." (PMID 23761779, 2013). "The development of several small cerebral infarcts is more likely to have contributed to the serum S-100B levels than potential traumatic lesions, in this case." (PMID 23227020, 2012). "In follow-up samples an inverse correlation was observed between ficolin-3 levels and concentration of S100β, an indicator of the size of cerebral infarct." (PMID 22206485, 2011). "Potential candidates for biomarkers of brain tissue injury, such as NSE and S100β, and it may be possible to detect the extent of cerebral infarction by measuring these serum markers." (PMID 39669376, 2024). "Indeed, polyphenols reduced brain infarct volume, hemorrhagic transformation (decreased cerebral level of hemoglobin), as well as plasma concentration of the glial marker S100β." (PMID 35624723, 2022). "Sustained elevations of S100B have been reported in the patients with large brain infarcts." (PMID 32922474, 2020). "Raabe and co-workers took daily S100B samples from their patients and found that a secondary increase of S100B >0.5 μg/l significantly correlated to the development of a severe secondary injury, such as a cerebral infarction or hematoma progression." (PMID 27957604, 2017). "Only one patient reached a peak level of serum S100B the day before vasospasm was confirmed (patient B), while the other patient reached peak S100B 1 day after angiographic confirmation of cerebral vasospasm and ongoing cerebral infarction (patient E)." (PMID 23761779, 2013). "S100b could be found in both CSF and blood serum of different brain diseases like brain tumors, neuroinflammatory and neurodegenerative disorders, psychiatric disorders, cerebral infections, subarachnoid hemorrhage, acute brain injury, and cerebral infarction." (PMID 33192985, 2020). "The secondary endpoints consisted of hospital cerebral infarction ascertained by CT and/or MRI, 30-day overall mortality, NSE levels and plasma S-100β levels were measured." (PMID 37746977, 2023).
cerebral infarction (continued). "Summary of the literature on CSF and serum S100B as biomolecular markers for radiographic vasospasm, DIND, delayed cerebral infarction and GOS outcome after aneurysmal SAH." (PMID 27007976, 2016). "Even so, these results demonstrate that S100B secondary elevation was likely to be related to cerebral infarction, and the putative origin of its release does not undermine this specific result." (PMID 33172087, 2020). "Pooled analysis was not generated for delayed cerebral infarction with CSF S100B as only two studies were included in this outcome, although both did not demonstrate a significant association." (PMID 27007976, 2016). "The increase in plasma S100β is not specific for cerebral infarction and can be observed with other neurological conditions such as TBI and extracranial malignancies, possibly leading to biased interpretations of results." (PMID 25029344, 2014). "Furthermore, serum S100B allowed the detection of cerebral infarction but not of CVS." (PMID 23509668, 2013).
cognitive decline (23 papers, 2013 to 2025). "More importantly, elevated levels of IL-1β and S-100β were associated with cognitive decline 1 w after surgery." (PMID 29249869, 2017). "Additionally, elevated S100B levels have been associated with cognitive decline, a hallmark of AD." (PMID 40487975, 2025). "Although there has been relatively little research on the association between S100β and age-related brain and cognitive decline, our findings that higher concentrations are related to poorer white matter FA could partly be related to deleterious effects due to systemic inflammation." (PMID 29933100, 2018). "Further research is necessary to determine whether oxytocin levels, in combination with other biomarkers such as S100B, can enhance the early detection of cognitive decline." (PMID 40487975, 2025). "Moreover, in a study investigating aging-associated cognitive decline, EPA and DHA at doses of 500 mg/kg/day were found to equally inhibit the mRNA expression of S100β in the hippocampus of aging rats." (PMID 39513898, 2024). "Rui-Lin Li indicated that RAGE signal transduction pathways mediated S-100β-induced neuro-inflammation, which might play a critical role in driving the pathogenesis of cognitive decline after surgery." (PMID 24236147, 2013). "Some authors demonstrated a significant correlation between S100B/ADMA levels and cognitive decline in patients with leukoaraiosis." (PMID 32340195, 2020).
mood disorder (22 papers, 2009 to 2025). A cognitive disorder a disturbance in which the person's mood is hypothesized to be the main underlying feature. "Altogether, our findings imply a small cause-effect relation for the previously reported associations of S100B and mood disorders." (PMID 37225692, 2023). "Only a few genetic association studies on S100B gene polymorphisms were conducted in mood disorders." (PMID 34099858, 2021). "S100B can be regarded as a potential diagnostic biomarker for mood disorders and as a biomarker for successful antidepressive treatment." (PMID 20585358, 2010). "However, we did find that increased S100B levels after 70 years of age had a causal effect on the risk of BIP—the other mood disorder included in our study." (PMID 37225692, 2023). "Our data indicates increased circulating S100B levels may causally associate with the lifetime risk of mood disorders." (PMID 37225692, 2023). "It is still unclear whether the different S100B protein levels observed in patients with mood disorders in different ages are associated with the progression of the disease or compensatory mechanisms." (PMID 34099858, 2021). "Disturbances in the blood–brain barrier permeability may be one of the factors that predispose to the occurrence of mood disorders, and being a useful biomarker of the changes in glial tissue, the S100B protein was considered." (PMID 34099858, 2021). "Existing research on BBBP in mood disorders thus far has utilized the “low hanging fruit” markers such as S100B—a calcium-binding protein localized to astrocytic end feet and a peripheral marker of BBB disruption—reviewed in a recent meta-analysis." (PMID 40046427, 2025). "A follow-up study from the Netherlands found that the activation of the inflammatory response system and patterns of change in chemokines and S100B, are essential in the events leading to the development of mood disorders." (PMID 38783266, 2024). "Serum S100B levels were measured in the adolescent groups with acute psychosis (n = 40), mood disorders (n = 40), and HC (n = 20)." (PMID 37759935, 2023). "We present a comprehensive study aimed at identifying the causal effects of circulating S100B levels on six neuropsychiatric or neurological disorders, including neurodevelopmental (ASD and SCZ), neurodegenerative (AD and PD), and mood disorders (BIP and MDD)." (PMID 37225692, 2023). "Stress is a risk factor for psychiatric disorders, including MDD37, and elevated levels of S100B have previously been found in serum and cerebral spinal fluid in people with mood disorders, including MDD21,38." (PMID 35585111, 2022). "It will be important to examine the effect of gender on serum S100B levels in a larger group of young patients with mood disorders in the future." (PMID 34099858, 2021). "According to our knowledge, this is the first prospective study that tries to explore the correlation between S100B serum levels and mood disorders in adolescents and young patients." (PMID 34099858, 2021). "In a prospective two-year follow-up study, peripheral levels of S100B were investigated in 79 adolescent/young adult patients (aged 14–24 years), diagnosed with mood disorders and compared with 31 healthy control subjects." (PMID 34099858, 2021). "The second study on adolescent groups (psychotic and with mood disorders) presents a significant elevation of S100B in patients with childhood trauma, compared to patients without trauma as well as controls." (PMID 34099858, 2021). "Aside from neurotrauma, additional variables, such as exercise, race, mood disorder diagnosis, and alcohol consumption, have been shown to have an influence on plasma S100B concentrations." (PMID 33096545, 2020). "S100B has been recognized as a potential treatment target in mood disorders and is confirmed as a mediator of depressive symptoms’ disabling cognitive effects by this analysis." (PMID 28594820, 2017).